LKAAEAR1 (LKAAEAR motif containing 1)
Synonyms: C20orf201
Tractability: No criterion of Open Targets' tractability assessment is met for any kind of drug.
Gene: Protein-coding gene on chromosome 20 (64,083,376 to 64,084,967, reverse strand). Ensembl gene ENSG00000171695.
Subcellular location (Human Protein Atlas): Nucleoplasm
Genetic constraint (gnomAD): Loss-of-function variants: 19 observed, 10.66 expected, observed/expected ratio (o/e) 1.78, 90% interval 1.18 to 1.96. The synonymous counts are far from expectation, so gnomAD's model fits this gene poorly and the ratio says little. Missense variants: 304 observed, 178.95 expected, observed/expected ratio (o/e) 1.7, 90% interval 1.55 to 1.87. Synonymous variants: 124 observed, 81.23 expected, observed/expected ratio (o/e) 1.53, 90% interval 1.32 to 1.77.
Homologues: Orthologues: macaque LKAAEAR1 (95% identical), chimpanzee LKAAEAR1 (90% identical), pig LKAAEAR1 (75% identical), rat Lkaaear1 (72% identical), mouse Lkaaear1 (69% identical), dog LKAAEAR1 (51% identical), tropical clawed frog lkaaear1 (31% identical).
Diseases named in the same sentence as LKAAEAR1 in open-access papers:
LKAAEAR1 is named in the same sentence as 1 disease in open-access papers, as found by Europe PMC text mining. Sharing a sentence is not in itself a finding about the gene and the disease.
LKAAEAR1 shares sentences with these, for which no sentence is quoted: colorectal cancer (1 paper).